INS (insulin)
Diseases named in the same sentence as INS in open-access papers (continued):
Sharing a sentence is not in itself a finding about the gene and the disease.
type 2 diabetes (continued). "Circulating plasma ceramides are higher amongst individuals with type 2 diabetes and studies have demonstrated an improvement in insulin signalling when ceramide degradation is stimulated." (PMID 38396205, 2024). "Over time, this feedback loop can lead to serious complications, especially in conditions like type 2 diabetes, where inflammation and insulin resistance perpetuate one another." (PMID 39896818, 2024). "In a study of Amouzad18, after 8 weeks of resistance training in patients with type 2 diabetes, their blood glucose, insulin, and insulin resistance index were significantly lowered as compared with the control group." (PMID 38307949, 2024). "Type 2 diabetes mellitus (T2DM) is a chronic disease caused by insufficient insulin utilization or efficiency, which is often accompanied by many complications, such as a series of cardiovascular and cerebrovascular diseases caused by abnormal lipid metabolism." (PMID 39703396, 2024). "Twelve semi-structured interviews were conducted amongst individuals with type 2 diabetes taking insulin who were enrolled in the 2GO-CGM randomised controlled trial and had completed 3 months of rtCGM." (PMID 38932793, 2024). "Type 2 ketosis is metabolically similar to type 2 diabetes, with both conditions exhibiting elevated insulin and glucose concentrations in the blood (transiently in cows with ketosis), interpreted as tissue insulin resistance." (PMID 38473200, 2024). "Roxadustat also improved the insulin-stimulated glycogen synthesis in this subgroup of myotubes from donors with type 2 diabetes (1.3-fold increase vs insulin-only condition) (p=0.0296)." (PMID 38814443, 2024). "Our study reported a decline in prescriptions of oral hypoglycaemics and an increase in insulin prescriptions among patients with type 2 diabetes." (PMID 38774927, 2024). "Type 2 diabetes (T2D) is a chronic adult-onset metabolic disorder characterized by high blood sugar due to insulin resistance or inadequate insulin production by pancreatic beta cells." (PMID 39659613, 2024). "Such misclassification can lead to inappropriate treatment regimens, including unnecessary lifelong insulin therapy, and hinder access to effective type 2 diabetes treatments." (PMID 39588334, 2024). "Here, insulin increased glycogen synthesis by 1.4-fold (p=0.0296) in myotubes from donors with type 2 diabetes, a response significantly reduced compared with that in myotubes from donors with NGT (p=0.0044)." (PMID 38814443, 2024). "In individuals with type 2 diabetes, there is often a deficiency or impaired function of GLP-1, leading to reduced insulin secretion and impaired glucose control." (PMID 38255264, 2024). "Her insulin dose requirements during pregnancy were similar to doses observed in women with type 2 diabetes." (PMID 38461278, 2024). "Although the glucose and insulin curves were slightly flatter in the MMTT than the OGTT, higher glucose responses in the MMTT were still associated with later development of type 2 diabetes." (PMID 38987291, 2024). "Exogenous insulin injections have been a primary treatment for both type 1 (T1D) and severe type 2 diabetes (T2D)." (PMID 38933536, 2024). "Pioglitazone (Piog) is a member of thiazolidinediones, insulin-sensitizing drugs, which improve insulin sensitivity and dyslipidemia in type 2 diabetics." (PMID 38441571, 2024). "Opportunities and needs for starting insulin therapy in Type 2 diabetes (T2D) have changed overtime." (PMID 38441838, 2024). "The significant reduction in phosphatidylcholine (PC) levels in newly diagnosed type 2 diabetes (T2D) patients and high-risk individuals indicates disrupted lipid metabolism, which may affect membrane integrity and insulin signaling." (PMID 39590846, 2024). "Those with type-2 diabetes and taking premix insulin, hypoglycemia occurred in 20.5% when compared with long-acting insulin 12.7%." (PMID 38827884, 2024).
type 2 diabetes (continued). "It is intriguing how from these data collectively an interplay emerges between insulin and glucagon pathways both involved in diabetes type 2, in which PON2 is involved." (PMID 38893310, 2024). "Lipid metabolites, such as ceramides, were shown to inhibit insulin signaling pathways and promote β-cell apoptosis, contributing to the progression of type 2 diabetes." (PMID 38920999, 2024). "Randomized controlled trials have found that once-weekly insulin resulted in greater glycemic control compared to once-daily insulin in patients with type 2 diabetes." (PMID 38172995, 2024). "Additionally, glucose and insulin responses were blunted after acute and repeated consumption of S&SE reformulated biscuits, which may confer a benefit for blood glucose control, for example in individuals at risk of developing type 2 diabetes." (PMID 38553262, 2024). "SMBG devices are universally considered to be an integral part of type 1 diabetes management and insulin-treated type 2 diabetes for optimizing the safety and efficacy of insulin regimens." (PMID 39361609, 2024). "Inflammatory cytokines interfere with insulin signaling, leading to insulin resistance, a key feature of type 2 diabetes." (PMID 39267632, 2024). "Basal insulin, mealtime insulin, and correction insulin strategies are similarly applied in type 2 diabetes, offering personalized approaches to optimize glycemic control." (PMID 39065795, 2024). "We recruit non-critically ill hospitalised general medical and orthopaedic patients with type 2 diabetes treated with basal, prandial, and correctional insulin (N = 166)." (PMID 38711112, 2024). "The comparable safety of Gla-100 and detemir and their superiority over NPH was attested by a study from Finland that reported a lower crude incidence rate for the first hypoglycemic coma event (per 100 person-years) with insulin detemir or Gla-100." (PMID 36896906, 2024). "Initiating insulin therapy in older individuals with type 2 diabetes (T2DM) poses unique challenges and requires a nuanced understanding of the age-related factors that impact safety and efficacy." (PMID 39074147, 2024). "A randomised crossover study in 26 adults with type 2 diabetes compared a fully closed-loop system with standard insulin therapy and a masked glucose sensor (control)." (PMID 38951212, 2024). "Persistent hyperglycemia is the main characterizing factor for prediabetes and type 2 diabetes diagnosis and results from cellular insulin resistance or insufficient insulin secretion from pancreatic B-islets to face blood glucose levels." (PMID 38164482, 2024). "Affordability was raised in particular regarding CGM, which is available through the NHS for all adults with type 1 diabetes and for some adults with type 2 diabetes (eg, if insulin-treated or other clinical need is identified)." (PMID 39446315, 2024). "The study explains the mechanisms of insulin resistance in sensory neurons in type 1 and type 2 diabetes, as well as the potential benefits of intrathecal injections of insulin and the neurotrophic effect of glucagon-like peptide-1 (GLP-1)." (PMID 38928135, 2024). "We aimed to review the clinical impact of SGLT2i and GLP1-ra therapy on the risk of diabetic retinopathy and diabetic macular oedema in individuals with type 2 diabetes taking insulin." (PMID 38584180, 2024). "There was a stepwise decline in insulin sensitivity (Si) from Lean-NGT to Obese-NGT to type 2 diabetes (p<0.0001)." (PMID 39138690, 2024). "The sensitivity of patients with type 2 diabetes to insulin is reduced, leading to insulin resistance, releasing free fatty acids (FFA), and increasing the possibility of FFA entering the liver." (PMID 39479695, 2024). "In contrast, in type 2 diabetes, peripheral target organs become resistant to the effects of insulin (i.e., insulin resistance builds up in the patient's body)." (PMID 38505447, 2024).
type 2 diabetes (continued). "Although many people with type 2 diabetes (T2D) get prescribed insulin therapy, glycaemic control is frequently insufficient in these individuals." (PMID 38659132, 2024). "Focus group findings revealed distressing insulin initiation experiences, inconsistent dietary advice, and perceived disparities in care between type 1 and type 2 diabetes." (PMID 39074147, 2024). "The risk factors encountered in the studied group were distributed as follows: 7 patients had type II diabetes, 2 of whom were insulin-dependent, 1 patient had thrombophilia and 2 patients had renal failure with peritoneal dialysis." (PMID 38617730, 2024). "Pdx1 is a transcription factor that is involved mainly in the formation of β cells, and a decrease in its expression leads to functional alterations in pancreatic insulin secretion and the development of type 2 diabetes in humans." (PMID 38673723, 2024). "A critical factor contributing to the onset of metabolic syndrome and consequent the decrease in sensitivity to insulin is the distribution of abdominal adipose tissue, which also represents a parameter that indicates the development of type 2 diabetes." (PMID 39224613, 2024). "It is known that exogenous insulin therapy and medications such as sulfonylureas or glinides, which are used to enhance the body’s natural insulin production in patients with type 2 diabetes, confer increased weight gain." (PMID 39174749, 2024). "A Mendelian randomization study on metabolic profiling of different glycemic traits suggests hyperglycemia-independent patterns and highlights the role of insulin in the development of type 2 diabetes." (PMID 38459184, 2024). "In the HEART2D trial, patients with type 2 diabetes following PCI were randomized to receive prandial versus basal insulin." (PMID 38558072, 2024). "The assessment of liver fat content through the NAFLD Liver Fat Score (NLFS) has proven to be accurate in diagnosing NAFLD and is computed considering factors such as metabolic syndrome, type-2 diabetes, fasting serum insulin, and AAR." (PMID 38473907, 2024). "The intervention was deconditioning for athletes and endurance exercise training for patients with type 2 diabetes, which influenced participants’ basal insulin sensitivity status." (PMID 38750012, 2024). "LY2405319 is another engineered FGF21 protein that is proven to be effective in a randomized clinical trial in obesity and type 2 diabetes patients, such as reducing body weight, fasting triglycerides, and insulin levels." (PMID 38292187, 2024). "While basal glycogen synthesis was unaffected by roxadustat, insulin-stimulated glycogen synthesis was enhanced by roxadustat pretreatment in myotubes from donors with type 2 diabetes (p=0.0345), to levels observed in myotubes from donors with NGT." (PMID 38814443, 2024). "With regard to type 2 diabetes, these studies investigated icodec in both insulin-naive and insulin-experienced individuals." (PMID 38679644, 2024). "The proportion of the mediation effect of type 2 diabetes ranged from 0.86% for acute pancreatitis to 7.73% for duodenal ulcer, and the proportion of mediation effect of fasting insulin ranged from 0.26% for cholelithiasis to 15.77% for alcohol liver disease." (PMID 38583262, 2024). "The global rise in obesity is fueling an increase in type-2 diabetes and other metabolic disorders, which are largely driven by resistance to insulin, the key hormone essential for governing glycemic levels and energy use and storage." (PMID 39033139, 2024). "Thiazolidinediones, a type of PPARγ agonist, are used to treat type 2 diabetes mellitus (T2DM) because its effect of promoting insulin sensitization, suggesting that PPARγ activation is beneficial to ameliorate diabetic cardiomyopathy." (PMID 38596692, 2024). "Metformin (N,N-dimethylbiguanide), an inhibitor of gluconeogenesis and insulin sensitizer, is widely used for the treatment of type 2 diabetes." (PMID 38461423, 2024).
type 2 diabetes (continued). "In both type 1 and type 2 diabetes a higher rate of hypoglycaemia was observed in individuals using human insulin, either alone or combined, than in those using analogue only insulin." (PMID 38795153, 2024). "In human, FXR activation can improve insulin sensitivity and reduce serum liver inflammatory markers in patients with type 2 diabetes and NASH." (PMID 38971765, 2024). "Targeting the β-TrCP/GSK3 axis would upregulate NRF2, improve beta cell function, slow the progression of type 2 diabetes and protect against the requirement for insulin treatment." (PMID 38479223, 2024). "Thiazolidinediones, peroxisome proliferator-activated receptor-gamma (PPAR-γ) activator, are compounds that enhance insulin sensitivity, effectively reducing plasma glucose levels and improving the lipid profile of individuals with type 2 diabetes." (PMID 38671903, 2024). "Bacteria endotoxins, such as lipopolysaccharides (LPS), have been detected in Type 2 diabetes, obese, and insulin-resistant mice, leading to increased adipose and systemic inflammation." (PMID 38474087, 2024). "Some studies were conducted to investigate the efficacy and safety of the two types of insulin analogues for type 2 diabetes, which represented the vast majority." (PMID 39588847, 2024). "Pancreatic β cell dysfunction is a key feature of type 2 diabetes, and novel regulators of insulin secretion are desirable." (PMID 38713514, 2024). "Metabolic-related outcomes include BMI, dyslipidemia, fasting plasma glucose, HDL cholesterol, HOMA-IR, insulin, overweight/obesity, percent body fat, type II diabetes (T2D), triglycerides, and waist-to-height adjusted BMI." (PMID 38128611, 2024). "Intriguingly, brain insulin sensitivity before a 24 month lifestyle intervention programme aiming to prevent type 2 diabetes predicted the programme’s effectiveness." (PMID 38363340, 2024). "The NAFLD score includes the presence of metabolic syndrome, type 2 diabetes, fasting concentrations of insulin, aspartate aminotransferase (AST), and the aspartate aminotransferase (AST)/alanine transaminase (ALT) ratio." (PMID 39609906, 2024). "Despite the benefits of blood glucose-lowering medications, including oral agents and exogenous insulin, in controlling the progression of type 2 diabetes and its complications, the safety of these drugs has been recently debated due to their side effects." (PMID 38778308, 2024). "The multitude of therapeutic options available makes treatment plans involving insulin unnecessarily complex for both clinicians and individuals with type 2 diabetes." (PMID 37787888, 2024). "A randomized clinical trial found that the use of WT by patients with type 2 diabetes led to significant reductions in weight, blood glucose, insulin, LDL-C, TC, and TG levels compared to their levels before the experiment and compared to the control group." (PMID 39768256, 2024). "The IVF-associated DMRs and the pathways in which they clustered were similar to ART result with additional terms such as insulin secretion (GO:BP), maturity onset diabetes of the young, and steroid biosynthesis (KEGG) (P < 0.05)." (PMID 39702541, 2024). "CGM is superior to capillary blood glucose monitoring for improving glycaemic patterns among insulin-treated patients with type 1 diabetes and type 2 diabetes, especially those with out-of-range glucose levels." (PMID 38907161, 2024). "The Hypo-RESOLVE database brought together prospective data on incident events following hypoglycaemia in type 1 and type 2 diabetes from clinical trials of glucose-lowering agents (all trials included insulin)." (PMID 39037602, 2024). "Of note, since the use of insulin pump is low in Type 2 diabetes in Italy, our results provide helpful information to support its use in this population of patients." (PMID 38197988, 2024). "This concept is consistent with the observation that impaired ATP homeostasis within the liver is a contributing factor to insulin sensitivity in patients with type 2 diabetes." (PMID 39608054, 2024).
type 2 diabetes (continued). "Initially, certain derivatives were used as insulin sensitizers for the treatment of Type 2 diabetes mellitus (T2DM) due to their PPAR-γ activation properties." (PMID 39065730, 2024). "Increased plasma SELENOP levels are also seen in type 2 diabetes because its biosynthesis is increased by high glucose concentrations and is suppressed by insulin." (PMID 39201524, 2024). "In other assays (qPCR, glycolytic rate, mitochondrial respiration), the five initial myotubes from donors with type 2 diabetes (three with a low insulin response and two with a robust insulin response in glycogen synthesis assays) were used." (PMID 38814443, 2024). "Currently, the main view of type 2 diabetes development suggests that insulin resistance in target tissues such as liver and muscle in combination with decreased insulin secretion leads to hyperglycemia." (PMID 39280605, 2024). "The patient, a middle-aged female with a 17-year history of type 2 diabetes, had been using Insulin Aspart 30 Injection for almost 10 years." (PMID 39575003, 2024). "Recently, a supplement of oleic acid (OA) and succinic acid (SA; 1 : 1, w/w) was reported to improve glycaemic control in type 2 diabetic (T2D) Sprague–Dawley (S-D) rats through ameliorating insulin release and sensitivity." (PMID 38938594, 2024). "We defined prototypical insulin secretion responses to three macronutrients in islets from 140 cadaveric donors, including those with type 2 diabetes." (PMID 38959864, 2024). "This study describes how the severity of initial presentation was related to glycemic control and prescribed insulin of children with type 2 diabetes treated at a single institution over 3 years." (PMID 38751370, 2024). "According to the multicenter Hypoglycemia Assessment Tool (HAT) Study, 83% of people with type 1 diabetes (T1D) and 46.5% of insulin-treated people with type 2 diabetes (T2D) had ever reported hypoglycemia." (PMID 38607977, 2024). "Despite the wide variety of hypoglycemic medications available, subjects with type 2 diabetes will eventually require insulin therapy with basal insulin being usually used as the initiation of insulin treatment." (PMID 39629047, 2024). "Blueberries have been found to improve insulin sensitivity, which is a critical factor in the management of type 2 diabetes." (PMID 39275275, 2024). "It promotes insulin secretion and inhibits glucagon release in a glucose-dependent manner, making it known as a treatment for type 2 diabetes." (PMID 39596109, 2024). "The authors concluded that the mild stimulation of GLP-1 and GIP was associated with a slower exogenous glucose rate increase, improved β-cell function (as these were type 2 diabetes patients), and reduced insulin clearance after OGTT." (PMID 39519472, 2024). "Hypoglycaemia requiring emergency assistance from health service personnel is also common in people with type 2 diabetes treated with insulin, and thus has a significant economic impact on the health care system." (PMID 38392992, 2024). "GATA3’s impact on metabolic disorders is being evaluated as well, particularly for adipogenesis and insulin sensitivity, which potentiates novel therapies for obesity and type 2 diabetes." (PMID 39768217, 2024). "We recruited 14 participants (50% women, 100% White, mean ± SD age 67±6 years, BMI 31±5 kg/m2, HbA1c 58±9 mmol/mol [7.4±0.9%]) with insulin-treated type 2 diabetes." (PMID 37922013, 2024). "Although fewer episodes are experienced by adults with insulin-treated type 2 diabetes, the frequency increases over time along with more individuals transitioning to insulin treatment." (PMID 39080044, 2024). "Being present in insulin-target tissues, chronic tissue inflammation has become recognized as a crucial aspect of obesity and type 2 diabetes." (PMID 39682569, 2024).